PCSK9 (proprotein convertase subtilisin/kexin type 9)
Diseases named in the same sentence as PCSK9 in open-access papers (continued):
Sharing a sentence is not in itself a finding about the gene and the disease.
Hypercholesterolemia (continued). "The use of PCSK9 mAbs has also been shown to lower the risk of myocardial infarction, ischemic stroke, and coronary revascularization in patients with hypercholesterolemia." (PMID 37568484, 2023). "Many studies have shown that mutations in the PCSK9 gene led to some diseases, such as hypercholesterolemia and atherosclerosis." (PMID 38077944, 2023). "A wealth of subsequent studies confirmed that an increase in circulating PCSK9 is associated not only with hypercholesterolemia but also with insulin resistance, increased glucose levels, and diabetes mellitus." (PMID 38028979, 2023). "Our results are consistent with the findings of clinical studies, indicating that a high-fat diet resulting in hypercholesterolemia and hypertriglyceridemia is associated with a higher risk of platelet activation and elevated PCSK9 levels." (PMID 37892538, 2023). "Obesity and hypercholesterolemia are known risk factors for cardiovascular diseases, and they are often treated with PCSK9 inhibitors." (PMID 37004042, 2023). "Subsequently, two dominant heterozygous missense mutations of PCSK9, p.S127R and p.F216L, were identified through DNA sequencing in three French families with hypercholesterolemia." (PMID 36935878, 2023). "On the contrary, a gain-of-function mutation in the PCSK9 gene (Arg499 → His) leads to familial hypercholesterolemia as a result of LDL receptor degradation." (PMID 37371118, 2023). "In humans, PCSK9 loss-of-function mutations are associated with hypocholesterolemia while gain-of-function mutations are associated with a familial hypercholesterolemia." (PMID 37004042, 2023). "The proprotein convertase subtilisin-like/kexin type 9 (PCSK9) gene is one of the major genes associated with familial hypercholesterolemia." (PMID 36655117, 2023). "Feeding a high-fat diet to mice transduced with an adeno-associated virus overexpressing the PCSK9 gene induces hypercholesterolemia and even atherosclerosis." (PMID 36970356, 2023). "On the other hand, gain-of-function mutations of PCSK9 result in familial hypercholesterolemia and increased cardiovascular risk, while loss-of-function mutations are associated with better lipid profile and confer to lower cardiovascular risk." (PMID 38094682, 2023). "Adeno-associated virus (AAV)-mediated overexpression of the mouse PCSK9 gain-of-function analog (D377Y) has been used to induce hypercholesterolemia in mice." (PMID 36243100, 2022). "The discovery that hypercholesterolemia in patients with nephrotic syndrome is associated with elevated levels of PCSK9 enabled the successful use of evolocumab in this novel indication." (PMID 35323699, 2022). "We discuss the potential role of defective PCSK9-LDL association in the development of hypercholesterolemia in humans." (PMID 36187800, 2022). "Adeno-associated virus (AAV)-mediated overexpression of PCSK9 was used to induce hypercholesterolemia to elicit atherosclerotic development in TRPM2+/+ and TRPM2−/− mice." (PMID 35563730, 2022). "In this systematic review and network meta-analysis, PCSK9 inhibitors, as adjuvant treatment in statin-treated hypercholesterolemia patients, were associated with greater reduction in atherogenic lipid level, including LDL-C, ApoB, and Lp(a)." (PMID 35444537, 2022). "The association between PCSK9 and hypercholesterolemia attracted numerous research groups to start an extensive investigation, resulting in the discovery moving from bench lab to clinical field in less than 10 years." (PMID 35207479, 2022). "Many missense mutations exist in PCSK9 gene, which can cause dominant hypercholesterolemia in patients, either by increasing the activity of PCSK9 or by giving it a new activity." (PMID 36552895, 2022).
Hypercholesterolemia (continued). "On another note, multiple mutations of PCSK9 can be found, which either induce higher activity, associated with hypercholesterolemia, or lower activity, associated with hypocholesterolemia." (PMID 36552895, 2022). "Genetic mutations responsible for amplification of PCSK9 activity are considered a potential cause of lethal familial hypercholesterolemia." (PMID 35806470, 2022). "Recently, a positive association of PCSK9 levels with adverse cardiovascular events has been observed in general population, in patients with familial hypercholesterolemia, in stable CAD, in atrial fibrillation, and in those undergoing PCI." (PMID 35596184, 2022). "Over the past 20 years, much has been learned about the PCSK9 pathway, stemming from the breakthrough finding in 2003 where gain of function mutations in PCSK9 were shown to be the third locus of familial hypercholesterolemia." (PMID 35956226, 2022). "Because of its lipid-lowering and cardiovascular properties, PCSK9-i therapy is crucial in subjects with a monogenic cause of high LDL-C such as familial hypercholesterolemia (FH)." (PMID 35885020, 2022). "Previous studies indicated that elevated PCSK9 levels correlated with increased risk of coronary artery calcification in patients with familial hypercholesterolemia under statin treatment." (PMID 35600486, 2022). "Gain-of-function mutations of the PCSK9 gene have been shown to cause familial hypercholesterolemia (FH), enhancing the risk for atherosclerosis and CVDs." (PMID 35683632, 2022). "Mutations of PCSK9 have been recognized as genetic markers of familial hypercholesterolemia (FH), whereas lower levels of LDL-C, as well as reduced risk of coronary heart diseases, were found in those with loss-of-function mutations." (PMID 35795514, 2022). "Mutations in PCSK9, a third locus associated with familial hypercholesterolemia, lead to a higher clearance of plasma LDL-C owing to reduced degradation of liver LDL-R." (PMID 36230934, 2022). "At present, PCSK9 inhibitors are recommended for patients with familial hypercholesterolemia and secondary prevention of high-risk patients who fail to reach the LDL-target despite optimal treatment or those intolerant to statins." (PMID 35456658, 2022). "Gain-of-function (GOF) point mutations in PCSK9 are associated with familial hypercholesterolemia (FH)." (PMID 36187800, 2022). "Our results provided the basis for a better understanding of the physiology of PCSK9 and the mechanisms underlying hypercholesterolemia." (PMID 34940619, 2021). "Its high expression in the liver and the presence of its gene on chromosome 1p32, led to the genetic association of gain-of-function (GOF) variants of PCSK9 with an autosomal dominant form of hypercholesterolemia." (PMID 34202098, 2021). "A gain of function mutation in PCSK9 in two French families that exhibit a dominant form of Familial Hypercholesterolemia suggested that reducing PCSK9 levels is an attractive mechanism to lower cholesterol." (PMID 34731223, 2021). "Proprotein convertase subtilisin/kexin type 9 is now an established target for correcting hypercholesterolemia and reducing ASCVD risk in high-risk patients, such as FH." (PMID 33643062, 2021). "The discovery of the marked effect of PCSK9 on LDL-C serum level has led to the rapid development of PCSK9 inhibitors for the treatment of hypercholesterolemia to reduce the risk of subsequent cardiovascular disease (CVD) development." (PMID 33692700, 2021).
Hypercholesterolemia (continued). "Once PCSK9 levels were linked with hypercholesterolemia, there have been many trials to assess different agents which block this interaction between PCSK9 and LDL receptors." (PMID 34462692, 2021). "Genetic studies have shown that gain-of-function mutations of the PCSK9 gene caused hypercholesterolemia, whereas loss-of-function mutations in PCSK9 resulted in hypocholesterolemia and reduced risk of cardiovascular disease." (PMID 34041285, 2021). "In a population of European ancestry, PCSK9 rs505151 polymorphism was reported in patients with hypercholesterolemia." (PMID 34876018, 2021). "Further supporting its role in CVDs, is the fact that various gain-of-function (GOF) mutations of PCSK9 are associated with hypercholesterolaemia and thereby an elevated risk for cardiac events." (PMID 34356856, 2021). "Because PCSK9 genetic gain-of-function mutations are associated with hypercholesterolemia, the pharmacological inhibition of PCSK9 is considered a promising route of intervention for preventing cardiovascular diseases." (PMID 34439528, 2021). "Pharmacological inhibition of PCSK9 (proprotein convertase subtilisin/kexin type 9) is an established therapeutic option to treat hypercholesterolemia, and plasma PCSK9 levels have been implicated in cardiovascular disease incidence." (PMID 34659352, 2021). "Genetic variants of PCSK9 are present in familial hypercholesterolemia and familial hypobetalipoproteinemia." (PMID 33829027, 2021). "The PCSK9 (proprotein convertase subtilisin/kexin type 9) gene is associated with familial hypercholesterolemia." (PMID 33829027, 2021). "PCSK9 is a novel therapeutic target for familial hypercholesterolemia designed for lowering cardiovascular risk (PCSK9 is observed in carotid atherosclerotic lesions) through monoclonal antibodies and small interfering RNA." (PMID 33807407, 2021). "Gain-of-function mutations in PCSK9 have been shown to cause familial hypercholesterolemia and increased cardiovascular risk." (PMID 34659352, 2021). "Kinetic studies of PCSK9 inhibition therapy on lipoprotein metabolism in diverse high risk patient populations (such as familial hypercholesterolemia) and new therapeutic combination also merit further investigation." (PMID 33643062, 2021). "When plasma PCSK9 was >267.60 ng/ml, the risk of developing hypercholesterolemia significantly increased in PNS patients (OR = 6.40, 95% CI 2.06–19.87, p = 0.001)." (PMID 32349585, 2020). "For example, a human genetic study in 2003 first reported that gain-of-function PCSK9 mutations led to hypercholesterolemia, after which the number of papers and citations began to increase." (PMID 33050894, 2020). "It is well known that PCSK9 gain-of-function mutations cause hypercholesterolemia and premature atherosclerosis, and PCSK9 inhibition is an emergent target in the treatment of ischemic heart disease." (PMID 32967202, 2020). "Coding variants in PCSK9 also cause hypercholesterolemia, and their association with LDL has been thoroughly studied and confirmed by the success of PCSK9 inhibitor therapies to lower cholesterol." (PMID 32687525, 2020). "The relevance of PCSK9 as a new molecular target for treating hypercholesterolemia and associated cardiovascular diseases is demonstrated by the clinical efficacy of two FDA/EMA-approved monoclonal antibodies: alirocumab and evolocumab." (PMID 32429343, 2020). "Recently, a technique to induce hypercholesterolemia in mice by an adeno-associated virus (AAV) mediated overexpression of the pro-protein convertase subtilisin/kexin type 9 (PCSK9) was developed." (PMID 32949971, 2020).
Hypercholesterolemia (continued). "Logistic regression analysis showed that when plasma PCSK9 was >267.60 ng/ml, the risk of developing hypercholesterolemia was significantly increased in PNS patients [odds ratio (OR) = 6.40, 95% CI 2.06–19.87, p = 0.001]." (PMID 32349585, 2020). "An increase in PCSK9 plasma levels, due to mutations in the PCSK9 gene and to pathophysiological determinants, causes dyslipidemia and hypercholesterolemia, risk factors for the development of CV diseases." (PMID 33158204, 2020). "Other cytokines such as IL-13 contribute to hypercholesterolemia associated with increased PCSK9 hepatic synthesis and enhanced circulating PCSK9 levels." (PMID 33262707, 2020). "While PCSK9 gain-of-function mutations cause hypercholesterolemia, loss-of-function mutations in the human or mouse gene result in low LDL cholesterol levels." (PMID 33575564, 2020). "Gain-of-function (GOF) mutations in PCSK9 result in familial hypercholesterolemia (FH), whereas loss-of-function (LOF) mutations are associated with life-long reductions in plasma LDL-C and significant protection from cardiovascular heart disease (4, –, 6)." (PMID 31949048, 2020). "Gain-of-function PCSK9 mutations associated with familial hypercholesterolemia (FH) and clustered at the predicted interdomain interface (R469W, R496W, and F515L) inhibited LDL binding, which was completely abolished in the case of the R496W variant." (PMID 31949048, 2020). "Gain-of-function mutations of PCSK9 cause severe hypercholesterolemia, whereas loss-of-function types lead to decreased circulating LDL cholesterol levels, protecting from cardiovascular disease (CVD)." (PMID 31114503, 2019). "Of note, W159 is also proximal to a loss-of-function variant of human PCSK9 that has previously been described as a nonsense allele protective against hypercholesterolemia and coronary heart disease." (PMID 30646909, 2019). "The ALN-PCS02 is a SNALP-formulated RNAi therapeutic targeting PCSK9 mRNA, encoding for Convertase Subtilisin/Kexin type 9 (PCSK9) protein for the treatment of hypercholesterolemia." (PMID 31344836, 2019). "The GOF mutations of PCSK9 cause hypercholesterolemia and a higher risk of atherosclerotic-related diseases." (PMID 31633088, 2019). "Gain-of-function mutations in PCSK9 gene causing over-expression of the plasma PCSK9 are associated with familial hypercholesterolemia (FH)." (PMID 31711505, 2019). "PCSK9 is the third gene identified in causing familial hypercholesterolemia (FH) in an autosomal dominant manner." (PMID 31633088, 2019). "The present study includes the use of HepG2 tumor xenograft model to study the potential role of glucose (by providing 15% glucose via drinking water) in regulating PCSK9 expression and associated hypercholesterolemia." (PMID 30386595, 2018). "PCSK9 regulates low-density lipoprotein cholesterol (LDLc) level and has been implicated in hypercholesterolemia." (PMID 30386595, 2018). "In the recent past, PCSK9 has drawn attention because of its role in dyslipidemia and proposition of it being a target in the management of hypercholesterolemia associated with cardiovascular disease." (PMID 30386595, 2018). "PCSK9 derived from tumor-graft increases on glucose feeding and likely to be associated with development of hypercholesterolemia in xenograft-bearing mice from group IV as compared to group III." (PMID 30386595, 2018). "Overall, this study illustrates tumor-secreted PCSK9 is induced by glucose availability, and its possible involvement in causing hypercholesterolemia in HCC." (PMID 30386595, 2018).
Hypercholesterolemia (continued). "PCSK9 was originally implicated in cardiovascular disease when human genetic studies identified gain-of-function PCSK9 mutations as a cause of familial hypercholesterolemia." (PMID 30251625, 2018). "Mutations in the PCSK9 gene are responsible for familial hypercholesterolemia that is a result of reduced LDL receptors on hepatocytes and reduced ability to remove LDL cholesterol from plasma." (PMID 30429826, 2018). "Of note many of the naturally occurring LOF mutations in PCSK9 result in altered proPCSK9 processing or reduced secretion from the cell, whereas mutations associated with hypercholesterolemia resulted in increased cellular exit of PCSK9." (PMID 28439730, 2017). "The expression of Pcsk9, associated with hypercholesterolemia, decreased after berberine treatment of HFD-induced obese mice." (PMID 29056891, 2017). "Heterozygous mutations in LDL Receptor, Apolipoprotein B, PCSK9, and Apolipoprotein E are linked to hypercholesterolemia." (PMID 29230236, 2017). "Insights into the physiological function of PCSK9 were derived initially from the recognition of functional mutations in the PCSK9 gene that cause an autosomal dominant form of hypercholesterolemia (ADH)." (PMID 28606094, 2017). "Plaque formation was studied by inducing hypercholesterolemia via adeno-associated virus delivery of PCSK9 followed by high fat feeding for 6 weeks." (PMID 27245171, 2016). "The development of therapies that inhibit PCSK9 function holds promise for improved management of hypercholesterolemia and CVD risk." (PMID 27424515, 2016). "GOF mutations of PCSK9 lead to hypercholesterolemia while non-sense mutations or LOF-mutations reduce the LDL-C concentration." (PMID 25600226, 2015). "The GOF-mutation (D374Y) of PCSK9 causes severe hypercholesterolemia and development of profound atherosclerotic lesions in mice and pigs." (PMID 25600226, 2015). "Gain-of-function mutations of PCSK9 are associated with hypercholesterolemia and increased risk of cardiovascular events." (PMID 25600226, 2015). "The observation that PCSK9 mutations cause dominant hypercholesterolemia suggests that mutations confer a gain-of-function." (PMID 23997648, 2013). "Among the PCSK family, mutations causing partial deficiency in PCSK1 have been linked to obesity, and mutations in PCSK9 are associated with hypercholesterolemia and coronary heart disease." (PMID 23936445, 2013). "Another protein that has been causally linked to familial hypercholesterolemia is proprotein convertase subtilisin/kexin type 9 (PCSK9)." (PMID 23430252, 2013). "Gain-of-function mutations of PCSK9 are associated with familial hypercholesterolemia and premature cardiovascular disease, while PCSK9 deficiency leads to low LDL cholesterol concentrations and protection against cardiovascular disease." (PMID 23544125, 2013). "Among these, the gene coding for convertase PCSK9 was discovered to be the third locus implicated in Familial Hypercholesterolemia (FH3)." (PMID 23951290, 2013). "Since its discovery, various missense mutations in PCSK9 have been shown to cosegregate with severe hypercholesterolemia in many families in several countries." (PMID 22111029, 2012).